FAP (fibroblast activation protein alpha)
Diseases named in the same sentence as FAP in open-access papers (continued):
Sharing a sentence is not in itself a finding about the gene and the disease.
ovarian carcinoma (continued). "FAP is overexpressed on the CAFs of ovarian cancer, and a study showed that the SUVmax of 68Ga-FAPI-04 for ovarian cancer was moderate, while FAPI showed low non-specific intestinal/peritoneal uptake rates." (PMID 35059319, 2021). "A combination of devices coated with anti-EpCAM or anti-fibroblast activation protein alpha (FAPα) antibodies were applied for patients with several kinds of cancers including ovarian cancer." (PMID 33327605, 2020). "PS1 was also found to colocalize with α-SMA and FAP in human ovarian cancer in vivo, which suggested that PS1 was located in the nucleus and secreted by CAFs." (PMID 32587587, 2020). "Yang’s study indicated that FAPα enhanced the migration and invasion ability of HO-8910PM cells (a highly metastatic ovarian cancer cell line) Additionally, FAPα increased HO-8910PM cell proliferation." (PMID 32850861, 2020). "Ovarian cancer cells treated in vitro with FAP showed significantly improved cell survival when exposed to cisplatin." (PMID 30927928, 2019). "Fibroblast activation protein alpha (FAP) expression in the stroma of epithelial ovarian cancer predicted the poor outcome of patients treated with cisplatin." (PMID 30927928, 2019). "Loss of SPHK1 in fibroblasts abrogated the induction of myofibroblast markers αSMA and FAP, and markedly diminished the ability of fibroblasts to contract collagen gels or induce ovarian cancer cell migration and invasion." (PMID 26716409, 2016). "Other genes such as FAP, CTSK, FBN1, THBS2, SPARC, and COL1A1 are also known to be ovarian cancer associated." (PMID 27843486, 2016). "The inflammatory cytokines IL-1β and TGF-β are reported to induce FAP expression in the highly metastatic ovarian cancer cell line HO-8910PM." (PMID 24551161, 2014). "Furthermore, elevated FAP expression in breast and ovarian cancers appears to correlate with advanced tumor grades and poorer prognosis." (PMID 40022239, 2025). "In accordance with the literature, Alpha-Smooth Muscle Actin (α-SMA), Integrin Beta-1 (CD29), the Fibroblast Activation Protein (FAP), Fibroblast-Specific Protein 1 (FSP1), and Platelet-Derived Growth Factor Beta Receptor (PDGFRβ), are fibroblast markers frequently associated with ovarian cancers." (PMID 39796089, 2024). "Similarly, FAP was found to be expressed at higher levels in advanced ovarian cancer, and silencing FAP induced apoptosis." (PMID 38063927, 2023). "Downregulating FAP-α with siRNA in SKOV3 cells inhibited ovarian tumor growth in nude mice whereas FAP-α overexpression in SKOV3 cells promoted ovarian cancer cell proliferation, drug resistance, invasiveness and migration in vitro, and tumor growth in vivo (BALB/c-nu/nu mice)." (PMID 36937451, 2023). "FAP is a cell surface serine protease that is highly expressed on the CASCs of various human cancer types, such as lung, prostate, pancreatic, colorectal, and ovarian cancer." (PMID 35211124, 2022). "HGSOC, the most common and lethal form of ovarian cancer, Upregulation of FAP was found in advanced stage HGSOC patients, showing association with poor prognosis via FN1 pathway, the association of FAP network shows FN1 can be a potential downstream gene leading to HGSOC survival." (PMID 35057823, 2022). "Moreover, high FAP expression in breast and ovarian cancer seems to correlate with advanced tumor grades and worse prognosis." (PMID 34050777, 2021). "Thereby, downregulated FAP+ fibroblasts could reduce the proliferation of tumor cells and might be a new treatment for ovarian cancer." (PMID 32850861, 2020). "Since FAP expression in ovarian cancers was shown to be associated with cancer promotion, invasion, chemoresistance, and worse clinical outcomes, it is not surprising that FAP theranostics have been suggested as potential adjuvants to existing treatment paradigms." (PMID 40604259, 2024).
ovarian carcinoma (continued). "FAP+CAFs promote the progression of various cancers, including gastric cancer, non-small cell lung cancer, prostate cancer, esophageal adenocarcinoma, clear cell renal cell carcinomas, ovarian cancer, and high-grade invasive urothelial carcinoma of the bladder." (PMID 37277751, 2023). "With respect to ovarian cancer, FAPI-PET/CT might be of particular interest as preceding studies determined its presence in 97% of all ovarian cancers and showed a correlation between FAP and a poor clinical prognosis, chemotherapy resistance and shorter time until recurrence." (PMID 34638433, 2021). "Expression of α‐smooth muscle actin (α‐SMA), fibroblast activation protein (FAP), and COL1A1 is higher in CAFs than NFs by qRT‐PCR and Western blot, indicating that we successfully established ovarian cancer CAFs and NFs." (PMID 40126173, 2025). "In breast cancer and ovarian cancer, four CAF subpopulations, CAF-S1 to CAF-S4, were identified with many markers, such as PDGFRβ, FAP, CD29, αSMA and S100A4." (PMID 38644492, 2024). "Four CAFs phenotypes in ovarian cancer have been characterized, mainly by the expression levels of α-SMA, FAP, and CD29." (PMID 35681617, 2022). "POSTN induced TGF-β2 expression from ovarian cancer cells to promote activation of adipose-derived stromal cells to become CAF-like cells expressing alpha smooth muscle actin and fibroblast activation protein alpha." (PMID 36550569, 2022). "In ovarian cancer, four subtypes of CAF populations (CAF-S1 to CAF-S4) have been discovered by analyzing CAF markers of FAP, α-SMA, CD29, PDGFRβ, FSP1, and caveolin 1 (CAV1)." (PMID 35681617, 2022). "Therefore, targeting FAP might present a potential pleiotropic antitumor strategy for epithelial ovarian cancer, as a high expression of FAP in CAFs has proven to influence proliferation, invasion, therapy resistance, shorter recurrence, and poor clinical outcome." (PMID 34050777, 2021). "In ovarian carcinomas, two different SMA-positive CAF sub-populations (FAP-high, SMA-positive vs. FAP-neg-low, SMA-positive) were shown for the first time to harbor heterogeneous metabolic programming amongst CAF cells in the same tumor type." (PMID 33808627, 2021). "Four different CAF subsets identified by analyzing specific CAF markers (FAP, integrin β1/CD29, αSMA, S100‐A4/FSP1, PDGFRβ, and CAV1) have been reported and related to immune modulation in human breast and ovarian cancers." (PMID 32909687, 2020). "In contrast, in ovarian cancer the epithelial cells transfer miR-124 to CAFs via exosomes, decreasing α-SMA and Fibroblast Activation Protein Alpha (FAP) expression and attenuated cell motility and thus reversing some traits of NFs." (PMID 31795332, 2019). "Similarly, EVs produced by ovarian carcinoma cells promoted the expression of α-SMA and FAP in normal ovarian primary fibroblasts." (PMID 36224527, 2022). "To evaluate the involvement of POSTN in modulating CAF activation, we surveyed the expression levels of CAF markers such as alpha smooth muscle actin (α-SMA) and fibroblast activation protein alpha (FAP) in the POSTN-high and POSTN-low ovarian cancer patients from the TCGA database." (PMID 36550569, 2022). "CAF markers that have been identified in ovarian cancer include α-SMA, FAP, FSP1, and FGF-1." (PMID 33808627, 2021). "It is also noticed that the origins of high COL1A1, COL1A2, and COL3A1 expression positively correlate with fibroblast-specific markers (FAP) and smooth muscle actin (ACTA2), whereas COL4A1, COL4A2, and COL18A1 seem to be predominantly expressed in ovarian cancer cells." (PMID 33026975, 2020). "For THY1 gene, though it was reported as a putative tumor suppressor of ovarian cancer, our study did not produce the same results as previous ones, despite THY1’s presence in our prediction of potential FAP association networks." (PMID 33109151, 2020). "Some studies have demonstrated that high FAP expression is a negative prognostic factor for epithelial ovarian cancer." (PMID 33109151, 2020).
ovarian carcinoma (continued). "TRS3 and INOF cells differentiated into CAF-like cells when cultured with ovarian cancer cell conditioned medium as evidenced by the induced expression of the CAF markers ACTA2, FAP, collagen 1α (COL1A1), fibronectin (FN1), and fibronectin with an alternatively spliced domain A (FN-EDA) (p < 0.05)." (PMID 26716409, 2016). "Among the common CAF-derived factors, FAPα has been shown to promote ovarian cancer proliferation and invasion via the engagement of α3β1 integrin receptor and the up-regulation of the ERK signaling pathway in ovarian cancer cells." (PMID 26751490, 2016). "In the areas of breast and ovarian cancer, CAF subtypes have been defined based on multicolor flow cytometry yielding the four subtypes depending on how they stained for the fibroblast markers FAP, CD29, αSMA, S100-A4, PDGFRβ, and CAV1, accumulating differently in different tumors." (PMID 37745296, 2023). "Besides FAPα, CAF-derived SDF-1, also known as CXCL12, has been shown to promote tumor growth, motility, and tumor angiogenesis in multiple cancer types, including ovarian cancer, by interacting with the CXCR4 receptors on cancer cells." (PMID 26751490, 2016). "The current results suggest that targeting FAP could have no pleiotropic anti-tumor effects, and anti-FAP therapy would be an ineffective treatment for ovarian cancer, although contrasting data suggested that FAP may be a candidate molecule for molecular targeting therapy." (PMID 29938002, 2018). "In addition, due to the limited therapeutic options for ovarian cancer, FAPI offers a potential therapeutic target as FAP expression is absent in healthy ovaries." (PMID 34638433, 2021).
gastric cancer (60 papers, 2010 to 2026). A primary or metastatic malignant neoplasm involving the stomach. "In gastric cancers, FAP expression by tumor epithelial cells is associated with increased cell proliferation, highlighting the role of FAP in tumor progression." (PMID 39765634, 2024). "CD10+ GPR77+ FAP+ CAFs were associated with chemoresistance and overall survival of advanced gastric cancer patients who underwent neoadjuvant chemotherapy (NCT)." (PMID 37480115, 2023). "It has been mentioned that FAP is one of the characteristic genes of gastric cancer and is associated with patient prognosis." (PMID 38063927, 2023). "Histological analysis of gastric cancer biopsy specimens also revealed that higher FAP expression is associated with a significantly greater density of microvessels." (PMID 34490078, 2021). "To further clarify whether the abundance of FAP+CAFs is associated with the efficacy of antitumor immune therapy in gastric cancer patients, we performed a retrospective analysis of peripheral blood immune cell subsets from 20 patients." (PMID 40843362, 2025). "Although previous studies have found an association between FAP+CAFs and tumor progression as well as immune evasion, whether FAP+CAFs play a significant role in immune evasion specifically in gastric cancer remains unclear." (PMID 40843362, 2025). "Similarly, elevated expression of FAP has also been associated with worse prognosis and promoting metastases in gastric cancer and KIRC, respectively." (PMID 39579201, 2024). "Moreover, elevated expression of FAP associated with chemoresistance and poor prognosis was reported in gastric cancer." (PMID 39579201, 2024). "FAP is highly expressed in gastric cancers and FAP levels may be associated with higher grades, peritoneal infiltration and a worse prognosis." (PMID 34638433, 2021). "In order to further investigate the clinical significance of FAP+CAFs in gastric cancer, the infiltration of FAP+CAFs was measured in 100 (stage IV) gastric cancer tissues using IHC." (PMID 40843362, 2025). "In this study, we identified significant variations in the expression levels of fibroblast activation protein (FAP) within CAFs across tumor tissues from various gastric cancer patients." (PMID 40843362, 2025). "To clarify the effect of FAP on IL-31 expression in CAFs cells, we isolated CAFs from two gastric cancer tissues and further upregulated FAP expression in CAFs using lentiviral vectors." (PMID 40843362, 2025). "Our findings expand upon previous studies by elucidating the specific role of FAP+CAFs in reshaping the immune landscape of gastric cancer, highlighting their potential as therapeutic targets." (PMID 40843362, 2025). "Studies in animal models have confirmed that FAP+ CAFs can inhibit the antitumor effect of T cells in the microenvironment of gastric cancer and enhance the antitumor effect of immune checkpoint blockers." (PMID 40485724, 2025). "Tumour cells expressing FAP include pancreatic adenocarcinoma, sarcoma, oesophageal and gastric cancers, colorectal cancer, mesothelioma, breast ductal adenocarcinoma, oral squamous cell carcinoma, glioma, ovarian, and cervical cancers." (PMID 40741380, 2025). "Our research identified a subset of CAFs derived from gastric cancer patients that exhibit high expression of FAP (FAP+CAFs) and demonstrate resistance to anti-PD-1 therapy." (PMID 40843362, 2025). "Studies involving gastric cancer biopsies showed increased micro-vessel density with cancers of higher FAP expression." (PMID 40741380, 2025). "In this study, we found high expression of FAP in CAFs from gastric cancer tissues resistant to anti-PD-1." (PMID 40843362, 2025). "In summary, our results reveal a novel mechanism by which IL-31 secreted by FAP+CAFs drives immune evasion in gastric cancer." (PMID 40843362, 2025).
gastric cancer (continued). "Here, our study uncovers a novel mechanism of CAF-mediated immune evasion in gastric cancer: FAP+CAFs facilitate the transition of naive CD4+ T cells toward a Th2 phenotype through IL-31 secretion." (PMID 40843362, 2025). "To further determine the role of FAP+CAFs in gastric cancer resistance to anti-PD-1, we analyzed retrospective data from another 24 primary gastric cancer patients receiving combined anti-PD-1 immunotherapy who had not received antitumor therapy." (PMID 40843362, 2025). "A few scenarios that reflected the potential role of FAP in promoting aggressive tumors were reported for breast, colorectal, pancreatic and gastric cancer." (PMID 39579201, 2024). "In gastric cancer, FAP expression is related to immunosuppressive cell infiltration, such as that of M2 macrophages (CD163+) and myeloid-derived suppressor cells (MDSCs) (CD11b+/CD33+)." (PMID 37143134, 2023). "In gastric cancer, stromal FAP promotes cancer progression via epithelial-mesenchymal transition (EMT) through Wnt/β-catenin signal pathway." (PMID 37316886, 2023). "A meta‐analysis of gastric cancer revealed that cases with high FAP expression were enriched in the gene pathways of cell growth." (PMID 36382346, 2023). "Some investigations revealed that FAP overexpression increases tumor angiogenesis in breast and gastric cancer." (PMID 37316886, 2023). "FAP+ cells enhanced abnormal angiogenesis by co-interaction with glioma cells, and FAP levels were positively correlated with angiogenesis in gastric cancer." (PMID 37006278, 2023). "Kumar et al17 recently suggested that the presence of a FAP+ and INHBA+ CAF subset is associated with poor prognosis of gastric cancer through single-cell transcriptomic analysis." (PMID 37196797, 2023). "MiR-30a targeted and inhibited FAP expression, thus resulting in the suppression of oral cancer or gastric cancer." (PMID 37166418, 2023). "It has been found that FAP+CAFs promote EMT of gastric cancer cells via the Wnt/β-catenin signaling pathway." (PMID 37277751, 2023). "Notch1 co-transfection partially reversed the effects of CSF2 on MSC phenotype and function, including the tropism towards gastric cancer cells, the enhanced FAP and α-SMA expression, and the secretion of GM-CSF, FGF, and PDGF-BB." (PMID 37865637, 2023). "It is known that FAP mediates tumor cell proliferation in gastric cancer via different pathways and thus enables metastasis formation by remodeling the tumor microenvironment." (PMID 34854061, 2022). "Functionally, silencing of INHBA affected FAP levels in gastric cancer CAFs, implying a potentially direct role for INHBA in regulating FAP expression, and consistent with TGFβ signaling as a mediator of INHBA." (PMID 34642171, 2022). "The Cox proportional hazard model of COL8A1, COL10A1, CTHRC1, and FAP and six tumor-infiltrating immune cells in gastric cancer (TIMER)." (PMID 35910202, 2022). "Analysis of gastric cancer (GC) patient tissue samples showed that FAP expression is positively correlated with micro-vessel density indicating the role of FAP expression in angiogenesis and metastasis." (PMID 35222418, 2022). "Taken collectively, these results highlight INHBA as a positive regulator of FAP in the gastric cancer STF3 fibroblast population." (PMID 34642171, 2022). "The results show that, due to the high expression of FAP in gastric cancer and its metastatic tissues, 68Ga-FAPI PET/MR is significantly superior to 18F-FDG PET/CT for the diagnosis of primary gastric cancer and its metastatic lesions." (PMID 34490078, 2021). "After 9 days of culture, western blotting assay showed that the expression of α-SMA and FAPα in the gastric cancer exosome-added MSC group was gradually upregulated compared to that in the MSC control group." (PMID 33731686, 2021). "In biopsies of gastric cancer, high FAP expression correlated with micro-vessel density vs gastric cancers with lower FAP expression." (PMID 32899119, 2020).